OGT (O-linked N-acetylglucosamine (GlcNAc) transferase)
Diseases named in the same sentence as OGT in open-access papers (continued):
Sharing a sentence is not in itself a finding about the gene and the disease.
Obesity (continued). "The specific regulation of this pathway by OGT was confirmed by overexpression of MBD2_v2, an obesity related gene that is downstream of OGT in the CSC pathway presented here." (PMID 37231419, 2023). "We showed that diet-induced obesity led to elevated tumor OGT expression and O-GlcNAc levels in mice compared to lean littermates, suggesting relevance of this pathway in an animal model of the hyperglycemic TNBC microenvironment." (PMID 37231419, 2023). "Because our data suggest that obesity and potentially other hyperglycemic diseases can both elevate OGT activity and drive a tumorigenic pathway in tumors, rising obesity rates are concerning with respect to the pathway we put together here." (PMID 37231419, 2023). "Genetic ablation of OGT in the VMH leads to obesity and reduced energy expenditure in mice fed a normal chow diet." (PMID 36044565, 2022). "Findings in mouse models indicate an evolutionarily-conserved role in regulating feeding behavior, as deletion of OGT in either the PVN neurons or pancreatic α cells induces overeating to the point of obesity." (PMID 36383567, 2022). "to explain the increase in insulin sensitivity and resistance to high-fat diet-induced obesity in mice with muscle OGT KO." (PMID 36058931, 2022). "Our study reveals an antiobesogenic role of OGT in the neural control of metabolism and suggests central OGT as a potential therapeutic target to combat obesity." (PMID 36044565, 2022). "Together, these data show that loss of OGT in SF1 neurons led to increased adiposity and obesity in mice." (PMID 36044565, 2022). "In an independent study, it was demonstrated that OGT ablation in white adipocytes of mice fed with HFD protected against diet-induced obesity and improves glycemic control." (PMID 35527999, 2022). "Specific and acute deletion of OGT in α-CaMKII-positive neurons in the PVN of male animals has been shown to induce obesity through hyperphagia in mice." (PMID 33460647, 2021). "The obesity phenotype in the constitutive male αOGTKO mice fed standard chow diet is supported by the described effect of OGT in the PVN in vivo." (PMID 33460647, 2021). "We found skeletal muscle O-GlcNAcylation plays an essential role in systemic energy homeostasis, and the deletion of skeletal muscle OGT (mKO) protects mice from high-fat diet-induced obesity and ameliorates whole-body insulin sensitivity." (PMID 34326778, 2021). "High fat diet induced insulin resistance, hyperphagia and obesity through O-GlcNAc cycling; thus, OGT can be a sensor for adipose to brain axis to target obesity." (PMID 31610620, 2019). "Together, these results demonstrate that the OGT drives diet-induced hyperphagia and obesity through signals determined by adipose tissue lipid desaturation." (PMID 30504766, 2018). "Removing OGT locally from αCaMKII neurons in the PVN in adult mice by stereotactic virus injection caused hyperphagia and obesity as well." (PMID 29790000, 2018). "Together, these results demonstrate that adipocyte OGT deletion abolishes HFD-induced obesity in mice." (PMID 30504766, 2018). "In the past decade, multiple laboratories including us have demonstrated the tremendous therapeutic potential of systematic inhibiting OGT in obesity-related cardiometabolic diseases." (PMID 30504766, 2018). "Here, we showed that adipocyte OGT is engaged during nutrient surplus, and is essential in the etiology of hyperphagia and obesity." (PMID 30504766, 2018). "Here we show that OGT in adipocytes mediates an adipose-to-brain signaling axis that enables hyperphagia and obesity during high-fat diet (HFD) feeding." (PMID 30504766, 2018). "That increased NEFA was positively correlated with increased monocytes in obesity and adipocyte OGT promotes monocytes development, we wondered whether NEFA could mediate the regulated effect of adipocyte OGT on monocyte." (PMID 40389445, 2025). "All these findings suggest that adipocyte OGT contributes to HFD-induced obesity." (PMID 40389445, 2025).
Obesity (continued). "Altogether, these preliminary data demonstrate a positive correlation between OGT and mTORC1 activity in islets from individuals who are lean in response to environmental stressors, whereas this response is altered in islets from patients with obesity." (PMID 39388284, 2024). "This combined human cell line and animal data suggest that obesity in humans might similarly lead to elevated OGT levels in TNBC tumors." (PMID 37231419, 2023). "Taken together, this data supports a yet-to-be confirmed hypothesis that obesity can elevate OGT expression and O-GlcNAcylation in tumors." (PMID 37231419, 2023). "On the other hand, OGT activity in liver cells has been linked to insulin and leptin resistance through STAT3 and PTP1B dependent pathways that are known to drive receptor desensitization in the hypothalamus, specifically in response to obesity." (PMID 36111295, 2022). "Nevertheless, sOGA and OGT activity in adipocytes appears to support adaptive functioning by adjusting lipolytic sensitivity while hyper-O-GlcNAcylation in obesity may limit metabolic flexibility by suppressing LD maturation and PLIN1-mediated lipolysis." (PMID 36111295, 2022). "After observing hyperphagia-induced obesity in the αOGTKO mice, we hypothesized that deletion of OGT was occurring in the PVN." (PMID 33460647, 2021). "To test whether OGT action is mediated through IL-15 in the context of obesity, we subjected mDKO mice to 22 weeks of a HFD." (PMID 34326778, 2021). "To test whether adipocyte OGT deletion abolishes diet-induced obesity through ablation of hyperphagia, we performed a pair-feeding experiment." (PMID 30504766, 2018). "Hence, a systematic approach to inhibit OGT represents a promising strategy to stop the epidemic of obesity and cardiometabolic diseases." (PMID 30504766, 2018). "Mechanistically, the regulated effect of adipocyte OGT on monocyte development may be mediated by NEFA-cluster of differentiation 36/fatty acid binding protein 4 (CD36/FABP4) pathway in HSCs in HFD-induced obesity." (PMID 40389445, 2025). "In addition to direct effects, OGT-driven changes in adipose insulin sensitivity and macrophage cytokine secretion may further fuel lipolytic dysfunction in obesity." (PMID 36111295, 2022). "It is reasonable to hypothesize that these relationships are less relevant in the fasting environment of elevated AgRP OGT activity, except perhaps in the case of obesity and its effects on the fasting milieu (e.g. systemically elevated glucose/insulin/lipids and ghrelin receptor desensitization)." (PMID 36111295, 2022). "Moreover, adipose OGT overexpression inhibits lipolysis and promotes diet-induced obesity." (PMID 31924761, 2020). "Using obese mouse models and adipocyte-specific OGT gene knockout mice fed with HFD, we demonstrated that obesity leads to changes in serum lipid profiles and promotes monocyte development via the up-regulation of OGT gene expression in adipocytes." (PMID 40389445, 2025). "Results showed significant tumor growth suppression in response to OGT inhibition, underscoring the critical role of YAP O‐GlcNAcylation and deubiquitylation in obesity‐driven tumor progression." (PMID 39868848, 2025). "Next, we investigated the effect of adipocyte OGT knockout on the obesity, and the results showed that the percentage of eWAT weight to body weight in HFD-OGT-AKO mice was significantly lower than that in HFD-WT mice." (PMID 40389445, 2025). "In first step, obesity triggers systemic hyperglycemia, which activates TET1 to produce higher levels of the DNA binding protein TARDBP via increased OGT substrate levels." (PMID 37231419, 2023). "Our findings have identified an antiobesogenic role of OGT in the VMH control of metabolism, as either chronic or acute deletion of OGT in VMH neurons reduces energy expenditure and induces obesity." (PMID 36044565, 2022).
Obesity (continued). "In this study, our analysis of a mouse model with adipocyte-specific ablation of OGT uncovers an unexpected fat-sensing OGT-SCD axis and defines its pivotal role in linking peripheral AEA metabolism with hyperphagia and obesity." (PMID 30504766, 2018). "While our study focused on EIF3H‐YAP interactions, future investigations should also explore whether EIF3H‐mediated OGT stabilization contributes to YAP regulation and obesity‐driven tumor progression." (PMID 39868848, 2025). "Mice lacking OGT in orexigenic neurons exhibit improved glucose metabolism and are protected from diet-induced obesity." (PMID 38566589, 2024). "Furthermore, proteins that target OGT and HBP flux are specifically dysregulated in response to obesity or HFD." (PMID 36111295, 2022). "Another X-linked gene is O-GlcNAc transferase (OGT), although its functions on body weight balance appears to be site specific, with OGT in orexigenic agouti-related peptide (AgRP) neurons promoting weight gain while OGT in anorexigenic PVH neurons prevent overeating and obesity." (PMID 33826123, 2022). "These conditions are potentially additive in progressed obesity, although the effects of OGT activity on non-gluconeogenic FOXO1 gene expression (e.g. MTTP) have not been tested." (PMID 36111295, 2022). "In obesity models, OGT and/or OGA protein were not always altered but when they were, it was generally consistent with the change in protein O-GlcNAcylation." (PMID 36111295, 2022). "Ablation of OGT, and thus O-GlcNAcylation, in skeletal muscle (mKO) resulted in increased energy expenditure, improved insulin sensitivity, protection against HFD-induced obesity, and dysregulation of muscle interleukin-15 (Il15) expression." (PMID 34326778, 2021). "However, it remains unknown whether OGT in adipocytes influences HSC differentiation, particularly in an obesity-prone environment." (PMID 40389445, 2025). "In addition, we do not imply that Treg function in coping with obesity is specifically controlled by OGT, but rather OGT is essential for most if not all Treg functions, including their regulation of insulin sensitivity and systemic metabolism." (PMID 35874700, 2022). "Specifically, targeting adipocyte OGT and its controlled downstream signaling pathways may treat obesity in a precise manner that would not interfere with mental health and homeostatic feeding." (PMID 30504766, 2018). "Future investigations into the source of this shift - whether differences in O-GlcNAc levels, OGT/OGA targeting, or the larger O-GlcNAc interactome – may prove fruitful in delineating and abrogating the self-sustaining pathways between progressive obesity and metabolic disease." (PMID 36111295, 2022). "However, following sustained obesity (18 weeks after HFD), OGT protein level decreases below normal levels." (PMID 39388284, 2024).
Hyperglycemia (23 papers, 2013 to 2025). An increased concentration of glucose in the blood. "Hyperglycemia-mediated increases in OGT and O-GlcNAc are associated with downregulation of miR-200a/200b, a class of microRNA with links to aging, diabetes mellitus, and arrhythmia." (PMID 38641064, 2024). "In the context of these reports, our results implicate a beneficial impact of SMC-targeted deficiency of OGT signaling in hyperglycemia-induced VSMC proatherogenic responses." (PMID 37175604, 2023). "The present study provides novel evidence for a causal role of smooth muscle OGT and O-GlcNAcylation in hyperglycemia-induced atherosclerosis." (PMID 37175604, 2023). "We envision that continued studies of OGT and O-GlcNAc-associated mechanisms in will help address hyperglycemia-associated cancer risk as a critical unmet challenge in oncology." (PMID 37231419, 2023). "Moreover, β cell‐specific OGT‐deficient mice displayed hyperglycemia with insulin depletion accompanied by β cell apoptosis." (PMID 39279604, 2025). "Because pre-menopausal TNBC risk and mortality are correlated with metabolic diseases, our results could lead to new directions including OGT inhibition for mitigating hyperglycemia as a risk factor for TNBC tumorigenesis and progression." (PMID 37231419, 2023). "Taken together, our data suggest that OGT-catalyzed O-GlcNAcylation may be a targetable link between hyperglycemia-associated diseases and TNBC risk through a CSC pathway that affects TNBC tumorigenesis." (PMID 37231419, 2023). "Furthermore, OGT loss caused hyperproinsulinemia, because of a failure of proinsulin-to-insulin processing, resulting in hyperglycemia and the appearance of the same defects in islets that are found in patients with type 2 diabetes." (PMID 35527999, 2022). "Rat aortic smooth muscle cells exposed to hyperglycemia display increased OGT abundance and O-GlcNAc levels." (PMID 38641064, 2024). "The studies conducted in this report indicated that hyperglycemia impacts CSC induction in TNBC via OGT-dependent glycosylation of TET1." (PMID 37231419, 2023). "The current report describes evidence to support that hyperglycemia drives OGT expression level and activity in a tumorigenic pathway identified in TNBC." (PMID 37231419, 2023). "Our data identified that hyperglycemia drove O-GlcNAcylation of the protein TET1 via OGT-catalyzed activity." (PMID 37231419, 2023). "Our data lends strong support to the notion that OGT promotes VSMC de-differentiation in response to hyperglycemia." (PMID 37175604, 2023). "Using biochemical approaches, genetic models, diet-induced obese animals, and chemical biology labeling, we evaluated the impact of hyperglycemia on CSC pathways driven by OGT in TNBC model systems." (PMID 37231419, 2023). "An interesting facet of this pathway was its feed-forward nature, whereby hyperglycemia led to enhanced activity of OGT, which in turn led to elevated OGT expression via the splicing factor TARDBP." (PMID 37231419, 2023). "Using inhibitors, RNA silencing, and overexpression engineering, we determined a potential hyperglycemia-promoted mechanism for upregulated OGT levels in TNBC that involves TET1." (PMID 37231419, 2023). "Collectively, these data clearly demonstrate a direct regulatory role of smooth muscle OGT on VSMC de-differentiation in response to hyperglycemia." (PMID 37175604, 2023). "In this report, we provide the first demonstration that smooth muscle OGT-dependent mechanism(s) drive atherosclerotic lesion formation stimulated by hyperglycemia." (PMID 37175604, 2023). "In conclusion, the present study uncovers a protective outcome of SMC-specific OGT deletion in hyperglycemia-induced atherosclerosis." (PMID 37175604, 2023). "As a nutrient sensor protein, OGT can integrate nutrient availability (i.e., hyperglycemia) and respond to physiological stressors to provide complex regulation of cell signaling, transcription, and translation." (PMID 35336721, 2022).
Hyperglycemia (continued). "Specifically, standard diet-fed mice harboring OGT deletion in β cells exhibited severe hyperglycemia, glucose intolerance, impaired insulin secretion and developed severe diabetes due to β cell failure." (PMID 35527999, 2022). "OGT has been considered to mediate several complications of hyperglycemia such as ER stress and mitochondrial dysfunction." (PMID 35336721, 2022). "In the embryos of diabetic mice, maternal hyperglycemia activates OGT and increases global protein O-GlcNAcylation." (PMID 28894244, 2017). "Our current study demonstrates an important role for OGT in hyperglycemia-induced embryonic malformations; however, its specific role in regulation of protein folding remains to be investigated." (PMID 28894244, 2017). "In this context, the development of macrophages specific OGT or OGA knock-out mice should provide important clues on the role of this modification in hyperglycemia-induced inflammation." (PMID 25620956, 2014). "Removing one genomic copy of OGT (sxc/+) led to increased hyperglycemia and significant heart dysfunction including increased arrhythmia and decreased fractional shortening in animals fed an LSD or HSD diet." (PMID 23326243, 2013). "Hyperglycemia leads to higher OGT substrate production (UDP-GlcNAc) in cells, and such elevated glucose to UDP-GlcNAc flux may outcompete the active site OGT inhibitor OSMI-4 in TNBC cells." (PMID 37231419, 2023). "Our data are comparable to these previous observations; specifically, in the current work, SMC-specific OGT deletion reduced SRF expression concomitant to attenuated PCNA expression in the aortic vasculature of smOGTKOApoE-/- following Western diet-induced hyperglycemia." (PMID 37175604, 2023). "As such, we speculate that interaction of YY1- and SRF-dependent pathways drive OGT-mediated SMC transformation to a de-differentiated phenotype in response to hyperglycemia." (PMID 37175604, 2023). "Notably, our data suggests that OGT-mediated O-GlcNAcylation regulates VSMC de-differentiation in response to hyperglycemia." (PMID 37175604, 2023). "To determine whether excess storage was due to hyperglycemia, we measured the glucose levels in the serum and found a significant decrease in the OGT-KO, indicating a flux of serum glucose to glycogen in the liver." (PMID 37930118, 2023). "Quantification of the ORO-positive area demonstrated a statistically significant reduction (p < 0.0001) in lipid-filled lesions formed in the aortic sinus of smOGTKOApoE-/- mice vs. smOGTWTApoE-/- with intact OGT, in response to Western diet-induced hyperglycemia." (PMID 37175604, 2023). "To confirm whether these maternal hyperglycemia-induced epigenetic changes were indeed due to increased O-GlcNAc levels, we injected pregnant hyperglycemic rats with OGT inhibitor ST045849 for 4 d (E9.5 to E13.4) and collected embryo brain cortices at E14.5." (PMID 35470239, 2022). "Therapeutic targeting of OGT could be a novel strategy to overcome the adverse effects of maternal hyperglycemia or similar metabolic perturbations." (PMID 35470239, 2022). "Hyperglycemia promotes the modification of the transcriptional regulator mSin3A by methylglyoxal in endothelial cells (ECs), triggering the increased O-GlcNAcylation of another transcriptional regulator, Sp3, via recruitment of OGT." (PMID 33086728, 2020). "For instance hyperglycemia promotes the methylglyoxal modification of mSin3A in ECs, triggering increased O-GlcNAcylation of the transcriptional regulator Sp3 via recruitment of OGT." (PMID 33086728, 2020). "The next question we wanted to address was whether OGT-catalyzed O-GlcNAcylation plays a role in mediating the effect of maternal hyperglycemia on NTD formation in the embryos." (PMID 28894244, 2017).